SUV39H2 (SUV39H2 histone lysine methyltransferase)
Diseases named in the same sentence as SUV39H2 in open-access papers (continued):
Sharing a sentence is not in itself a finding about the gene and the disease.
metabolic dysfunction-associated steatohepatitis (2 papers, 2021 to 2025). Metabolic dysfunction-associated steatohepatitis (MASH, formerly known as nonalcoholic steatohepatitis or NASH) is a type of fatty liver disease. "Suppressor of variegation 3–9 homolog 2 (SUV39H2) or KMT1B-mediated H3K9me3 accelerates hepatocarcinogenesis by contributing to non-alcoholic steatohepatitis in mice." (PMID 34901003, 2021). "Notably, Angiogenic factor with G patch and FHA domains 1 (AGGF1) regulates liver fibrosis and may contribute to Metabolic dysfunction-associated steatohepatitis (MASH) pathogenesis just like Vanin-1 (VNN1) and Suv39h2, two histone methyltransferases." (PMID 41272759, 2025).
adenoma (1 paper, 2013). A neoplasm arising from the epithelium. "Quantitative analysis of microarray data confirmed that these methyltransferases, which included Setd3, Setd5, Suv39h2, Smyd3, Prmt3, Prmt6, Nsd1, and Nsd2 were up-regulated in metastases compared to adenomas, carcinomas, or disseminated cells." (PMID 23520493, 2013).
autoimmune disease (1 paper, 2021). A disorder resulting from loss of function or tissue destruction of an organ or multiple organs, arising from humoral or cellular immune responses of the individual to their own tissue constituents. "SUV39H2 downregulation has been also associated with autoimmune diseases." (PMID 33602320, 2021).
glioblastoma (1 paper, 2020). The most malignant astrocytic tumor (WHO grade IV). "Intriguingly, Trametinib appeared to specifically reduce ZNF263 protein levels without altering those of KAP1, SUV39H2, EED, or SETDB1, implying that the activation of EGFR/MAPK led to SIX3 silencing in glioblastoma mainly through the regulation of ZNF263." (PMID 32051553, 2020).
oral cancer (1 paper, 2024). "In the nucleus, histone-modifying enzymes, such as SETDB1, SUV39H2, and KMT2A were also associated with areca nuts, suggesting that areca nut-induced mutations also deregulate the expression and silencing of various genes that can promote oral cancer development and progression." (PMID 39027148, 2024).
oral squamous cell carcinoma (1 paper, 2025). "Here, through genome-wide CRISPR/Cas9 library screening, Suppressor of variegation 3–9 homolog 2 (SUV39H2), a histone methyltransferase, was identified as a critical factor in mediating resistance to oncolytic herpes simplex virus 1 (oHSV-1) in oral squamous cell carcinoma (OSCC)." (PMID 40849299, 2025).
triple-negative breast carcinoma (1 paper, 2025). An invasive breast carcinoma which is negative for expression of estrogen receptor (ER), progesterone receptor (PR), and human epidermal growth factor receptor 2 (HER2). "SUV39H2 is consistently upregulated in triple-negative breast cancer and is associated with malignant features including enhanced proliferation, migration, stemness, and in vivo tumorigenicity." (PMID 41551146, 2025).
cancer (23 papers, 2006 to 2025). A tumor composed of atypical neoplastic, often pleomorphic cells that invade other tissues. "TCGA database analysis revealed that SUV39H2 is associated with distinct immune cell infiltration patterns across different cancer types and correlates with immune checkpoint expression." (PMID 40849299, 2025). "The important role of SUV39H2 in cancer is further illustrated by the finding that somatic mutations in this (and other PKMTs) are observed in tumor tissues." (PMID 34357075, 2021). "In the double knockout Suv39h1/Suv39h2 mouse the reduced level of H3 K9 methylation is associated with genomeinstability and predisposition to cancer." (PMID 16638127, 2006). "We also screened HDAC1, HDAC2, SUV39H1, and SUV39H2 for mutations in 65 cancer cell lines and 116 primary tumours." (PMID 16638127, 2006). "Mutation analysis of HDAC1, HDAC2, SUV39H1, and SUV39H2 revealed only two out of 181 cancer samples (both cell lines) with significant coding-sequence alterations." (PMID 16638127, 2006). "In the CC category, SUV39H2 was associated with cellular communication in both cancers." (PMID 41551146, 2025). "SUV39H2 mainly participates in the occurrence and development of cancer as an oncogene, including invasion and metastasis." (PMID 39981438, 2025). "SUV39H2, a histone methyltransferase involved in H3K9 trimethylation and transcriptional silencing, has been implicated in cancer progression." (PMID 41551146, 2025). "Their prognostic significance varies across cancer types, with SUV39H1 expression showing context-dependent risk, while SUV39H2 high expression typically indicates an unfavorable prognosis." (PMID 40849299, 2025). "SUV39H2 was significantly overexpressed in multiple cancers, with consistently elevated levels in paired tumor-adjacent tissues." (PMID 41551146, 2025). "A previous study showed that overexpression of SUV39H2 contributed to the progression of cancer, and this phenomenon is the opposite of the aging process." (PMID 34559682, 2021). "Accumulating evidence indicates that SUV39H2 acts mainly as an oncogene that contributes to the initiation and progression of cancers including invasion and metastasis." (PMID 34357075, 2021). "Both SUV39H1 and SUV39H2 are prognostic markers for different cancers, but dependent on the tumor type, either a high or low expression of SUV39H1 constitutes a risk, while a high expression of SUV39H2 is unfavorable in most cases." (PMID 34357075, 2021). "Our data have shown that SUV39H2 inhibition plays important regulatory roles in γ-H2AX production in cancer cells by these two small-molecular compounds." (PMID 30159125, 2018). "Our results suggest that the SUV39H2 inhibitors sensitize cancer cells to DOX by reduction of γ-H2AX levels in cancer cells, and collectively demonstrate that SUV39H2 inhibition warrants further investigation as a novel anti-cancer therapy." (PMID 30159125, 2018). "We previously reported that the histone lysine methyltransferase SUV39H2, which is overexpressed in various types of human cancer, plays a critical role in the DNA repair after double strand breakage, and possesses oncogenic activity." (PMID 26988914, 2016). "We previously reported that SUV39H2 was overexpressed in various types of cancer, while its expression is hardly detectable in normal tissues except testis." (PMID 26988914, 2016). "Our study indicated a high correlation between SUV39H2 and LSD1, which imply a new viable approach combining LSD1 and SUV39H2 inhibitors in cancer therapy." (PMID 26183527, 2015). "Along with epigenetic modifiers that were previously implicated in cancer cell fitness, such as CHD1, CHD4, DNMT3B, ELP3, SUPT16H, SUV39H2; novel hits ASH2L, RBX1 and SSRP1 were discovered as essential genes for both U373 and T98G cells suggesting common regulatory role." (PMID 37974198, 2023).
cancer (continued). "Whereas the roles of the histone methyltransferases SUV39H1 and SUV39H2 have been investigated in the context of cancer in humans and mice, the role of SUV39H2 in epidermal differentiation in mice, humans and dogs is virtually unknown." (PMID 32119674, 2020). "Previous studies reported that chaetocin could reduce suv39h1, suv39h2, and G9a mRNA or their protein in ovine cells and human cancer cells." (PMID 32650566, 2020). "Furthermore, our expression profile analysis revealed SUV39H2 to be highly expressed in many cancer types, while its expression levels are very low or hardly detectable in normal tissues except adult testis." (PMID 30159125, 2018). "Dysregulation of SUV39H2 expression has been observed in several types of cancers." (PMID 30348215, 2018). "Henceforward, owing to the intricate relationship between SUV39H2 and γ-H2AX formation, we speculated that SUV39H2 inhibition may be a promising potential drug target in various types of human cancer." (PMID 30159125, 2018). "As such, SUV39H2-mediated methylation has an impact on tumorigenesis both through methylation of histone and non-histone substrates, and SUV39H2 genetic alterations have been reported in many cancer types." (PMID 30159125, 2018). "In addition, SUV39H2-dependent histone H2AX methylation directly affects the level of γ-H2AX activity that regulates the DNA repair pathway in human cancer, and we confirmed that SUV39H2 possesses oncogenic activity." (PMID 26988914, 2016). "In addition, SUV39H2 shows oncogenic activity, and knockdown of SUV39H2 by specific siRNAs suppresses the growth of cancer cells, suggesting that SUV39H2 appears to be an ideal target for the development of anti-cancer therapy." (PMID 26988914, 2016). "Overexpression of SUV39h1 and SUV39H2 has been reported in various cancers." (PMID 26695186, 2015). "Taking these findings into account, we propose a SUV39H2 inhibitor could be used alone or in combination with DNA-damaging agents or radiotherapy in cancer patients with aberrant SUV39H2 expression." (PMID 25487737, 2014). "Importantly, SUV39H2 expression was restricted to adult testis in normal tissues and was highly elevated in a variety of tumor types, thus making it an ideal target for anti-cancer drug development." (PMID 30159125, 2018). "Indeed, as the expression level of SUV39H2 in normal tissues is low, this molecule could represent an ideal target for cancer therapy." (PMID 25487737, 2014). "Suppressor of variegation 3-9 homolog 2 (SUV39H2/KMT1B), a member of the SUV39 subfamily of lysine methyltransferases (KMTs), functions as an oncogene in various types of cancers." (PMID 34559682, 2021). "Given that SUV39H2 is significantly upregulated in various types of tumour tissues, it is possible that constitutive SUV39H2 overexpression in cancer cells may cause aberrant γ-H2AX expression, and that cancer cells might acquire more malignant phenotype, including chemo- and/or radioresistance." (PMID 25487737, 2014). "In the present study, we showed that the histone methyltransferase SUV39H2 methylates histone H2AX on lysine 134, and that this is critical for the production of γ-H2AX in cancer cells." (PMID 25487737, 2014). "In addition, SUV39H1 and SUV39H2 are also markers for the development of different cancers, with high or low expression of SUV39H1 posing risks, while high expression of SUV39H2 is often detrimental in most cases." (PMID 40750792, 2025). "Cancer-related genes such as FAS, P16, P21, Twist1, which mainly function as tumor suppressor genes, are inhibited by the overexpression of SUV39H2, while oncogenes such as PSA and C-myc are enhanced by the overexpression of SUV39H2." (PMID 39981438, 2025). "The results suggested that knockdown of SUV39H2 might have an impact on a series of pathways including metabolism in cancer, TGF-β signaling pathway, Hippo signaling pathway, and pathways in cancer." (PMID 30348215, 2018).
cancer (continued). "Although SUV39H2 is considered as one of the promising targets for anti-cancer drug development, the regulatory mechanism of SUV39H2 activity by post-translational modification is still not well known." (PMID 26988914, 2016). "Notably, SUV39H2 expression is present only in cancer cells but not in normal cells (apart from testis)." (PMID 39519018, 2024).
tumor (18 papers, 2006 to 2025). "We also probed the molecular basis that might cause the specific overexpression of SUV39H2 in tumor cells." (PMID 30348215, 2018). "Identification of the target genes regulated by SUV39H2 might further elucidate the molecular mechanisms underlying its overexpression in tumor tissues." (PMID 30348215, 2018). "Due to the lack of paired samples for ACC and SARC in the TCGA dataset, paired sample analysis focused on BRCA and LIHC, revealing significantly elevated SUV39H2 expression in these two tumor types." (PMID 41551146, 2025). "SUV39H2 mediates H3K9me3 modification, promoting tumor progression, poor survival outcomes, and chemoresistance." (PMID 40949882, 2025). "SUV39H2 was found to be significantly overexpressed in multiple tumor types, including ACC, BRCA, LIHC, and SARC, with this elevated expression also evident in matched adjacent normal tissues." (PMID 41551146, 2025). "Analysis of serum exosomes and tumor tissues from NSCLC patients demonstrated that miR-let-7e was low, and suppressor of variegation 3-9 homolog 2 (SUV39H2) was high in NSCLC tissues and was associated with low OS." (PMID 33740988, 2021). "As tumor initiation is one of the critical roles of GSCs, we conducted an in vivo tumor initiation assay to further demonstrate the role of SUV39H2 in sustaining GSC stemness." (PMID 31636512, 2019). "Then, we identified that the amplification percentages of SUV39H2 in different tumor stages were consistently higher than those of SUV39H1." (PMID 30348215, 2018). "Through bioinformatics analyses, we found that SUV39H2 underwent a severe upregulation in the tumor tissue, which was also confirmed in the surgically removed tissues." (PMID 30348215, 2018). "Moreover, according to the nonparametric test of the data, we found that the expression level of SUV39H2 was correlated with the CNA of the gene, which implies that the gain of copy number in tumor cells might be the underlying mechanism that causes SUV39H2 overexpression." (PMID 30348215, 2018). "A number of histone methyltransferases, including Setd3, Setd5, Suv39h2, Smyd3, Prmt3, Prmt6, Nsd1, and Nsd2, were up-regulated in metastases compared to disseminated tumor cells or primary tumors." (PMID 23520493, 2013). "InIn BRCA and LIHC, SUV39H2 overexpression was further associated with clinical features such as younger patient age, advanced T stage, and molecular subtypes, suggesting that SUV39H2 may contribute to more aggressive tumor phenotypes." (PMID 41551146, 2025). "Together, these results suggest that SUV39H2 may regulate peptidase activity and promote tumor cell development and differentiation through this pathway." (PMID 41551146, 2025). "For example, SUV39H2 (also known as KTM1B) is expressed in nearly all tumor types." (PMID 33348709, 2020). "The knockdown of SUV39H2 severely impaired the tumor growth in situ." (PMID 30348215, 2018). "Next, we investigated the role of SUV39H2 in tumor progression in vivo." (PMID 30348215, 2018). "Moreover, we found TPM4 and CCDC80, which were reported to exert a tumor repression activity, to be upregulated due to SUV39H2 knockdown." (PMID 30348215, 2018). "Results demonstrated that SUV39H2 expression was significantly elevated in tumor tissue samples." (PMID 30348215, 2018). "The seven genes comprising the HMR model (SUZ12, KAT2A, AURKA, BUB1, SUV39H2, UTY, and PCGF5) are critically involved in epigenetic modification, tumor progression, supporting their prognostic value in MM." (PMID 40949882, 2025). "SUV39H2 was known to be related to DNA repair by methylating the histone H2AX, indicating a tumor-promoting activity." (PMID 30348215, 2018). "Due to the potential regulation of SUV39H2 over OPTN and the tumor-repressive activity of OPTN, we next conducted clone formation assays in the A549 cells with SUV39H2 knockdown." (PMID 30348215, 2018). "Several novel genes also positively correlated with TN disease, high Ki67 levels and tumor grade: DNMT3B, SUV39H1 and SUV39H2." (PMID 27863398, 2016).
tumor (continued). "Moreover, elevated SUV39H2 expression was strongly correlated with poor prognosis, including worse OS, DSS, and PFI, underscoring its potential role in tumor development." (PMID 41551146, 2025). "Furthermore, SUV39H2 inhibition significantly enhances oHSV-1 replication within tumor tissues and promotes CD4+ T and CD8+ T immune cell infiltration into the tumor microenvironment, ultimately improving the virus’s oncolytic efficacy." (PMID 40849299, 2025). "Deletion of this gene allows for partial elongation of telomeres, thereby aiding tumor growth, suggesting that the presence of SUV39H2 is unlikely to promote tumor growth." (PMID 33348709, 2020). "In addition to the 8 representative PKMTs with tumor suppressor activity, PRDM16, MLL2, MLL4, SET domain bifurcated histone lysine methyltransferase 1 (SETDB1), SETD3, NSD1, NSD3, DOT1L, SUV39H1, and SUV39H2 have also been suggested to possess tumor suppressor activity." (PMID 38036730, 2023). "However, SUV39H2 expression did not significantly correlate with the tumor stages of patients with NSCLC." (PMID 33658396, 2021).
infection (1 paper, 2025). The state of being infected such as from the introduction of a foreign agent such as serum, vaccine, antigenic substance or organism. "Western blotting revealed no significant alterations in SUV39H2 protein abundance at 12 hpi across all MOI conditions, suggesting that the early phase of infection does not trigger its immediate degradation." (PMID 40849299, 2025).
SUV39H2 also shares sentences with these, for which no sentence is quoted: leukemia (3 papers); osteosarcoma (3); bladder cancer (2); hepatocellular carcinoma (2); lymphoma (2); acute lymphoblastic leukemia (1); ameloblastoma (1); autism spectrum disorder (1); Breast Invasive Carcinoma (1); colon carcinoma (1); Diabetic Nephropathy (1); head and neck cancer (1); IgA vasculitis (1); large cell lung carcinoma (1); liver cancer (1); liver disease (1); liver fibrosis (1); melanoma (1); migraine (1); pancreatic adenocarcinoma (1); renal carcinoma (1); retinopathy (1); soft tissue sarcoma (1); squamous cell carcinoma (1); squamous cell lung carcinoma (1); thyroid cancer (1).